HDAC1 (histone deacetylase 1)
Diseases named in the same sentence as HDAC1 in open-access papers (continued):
Sharing a sentence is not in itself a finding about the gene and the disease.
tumor (continued). "Enhanced HDAC-1 expression was significantly associated with increased tumor proliferative capacity (p = 0.0238) and borderline with the absence of lymph node metastases (p = 0.0632)." (PMID 26502922, 2015). "In the present study, the roles of the c-Myc/Skp2/Fbw7 and HDAC1/2 pathways, which are associated with tumor progression, on the anticancer effects of AMP in the A549 NSCLC line were investigated." (PMID 25333250, 2015). "We also aimed to evaluate the association of HDAC-1, −2, −4 and −6 expression with clinicopathological characteristics, tumor proliferative capacity and patients’ survival." (PMID 26502922, 2015). "In crosstabulation, high HDAC-1 expression was significantly associated with increased tumor proliferative capacity (p = 0.0238)." (PMID 26502922, 2015). "In accordance with this idea, total deacetylase and co-repressor activity was unchanged in Hdac1Δ/Δep epidermis but clearly reduced in HDAC1-deficient tumours." (PMID 24240174, 2013). "HDAC1-deficient tumours showed hyperproliferation of the basal and suprabasal layers as determined by Ki67 staining and reduced expression of the epidermal differentiation marker K10." (PMID 24240174, 2013). "Our data suggests that down-regulation of claudin-6 is an important factor influencing lymphatic metastasis; whereas up-regulation of HDAC1 is associated with tumor progression and invasiveness in breast IDC." (PMID 22455563, 2012). "Xu found that claudin-6 is an important factor influencing lymphatic metastasis, whereas up-regulation of HDAC1 is associated with tumor progression and invasiveness in breast IDC." (PMID 23276146, 2012). "The overall tumor growth rate and volume were significantly reduced in HDAC1 deficient cell line (HDAC1KD#1) compared to the control (Mock#1) (p<0.05)." (PMID 22496786, 2012). "Paradoxically, HDAC1 can negatively regulate transcription of a number of cell cycle genes associated with proliferation as well as tumor suppression." (PMID 17578512, 2007). "In a sub-group of ER/PGR-positive, HER2-negative tumours, expression of HDAC-1 was associated with a better DFS probability then HDAC-1 negative tumours." (PMID 16595007, 2006). "This further supports the idea that replicative senescence, and the associated decline in HDAC1 expression, has a tumor suppressing role." (PMID 16250917, 2005). "The switch in immunophenotype and the hyperactivated oncogenic signaling including the PDGFRB-STAT5-IL10 oncogenic axis might suggest epigenetic reprogramming of ALK+ tumor cells upon loss of HDAC1." (PMID 40175628, 2025). "Treatment with HDAC1 inhibitors cause release of HDAC1 protein from the Sp1 (Promoter-specific RNA Polymerase II transcription factor), and promote p21 transcription and regulation of tumor growth." (PMID 40581884, 2025). "However, high levels of HDAC1 have been found in different tumor types and have been associated with poor survival." (PMID 37696456, 2023). "Furthermore, we identified upregulated DEGs in TN tumours including drug targets histone deacetylase enzymes (e.g. HDAC1, HDAC2, and HDAC11) implicated in the epigenetic regulation of gene expression." (PMID 36220861, 2022). "A multi-omics study in liposarcoma shows that HDAC1 is mutated in 8.5% of primary tumours." (PMID 34298745, 2021). "Additionally, HDAC-1 was associated with increased tumor size, HDAC-6 with mitotic index, and HDAC-2 with epithelioid cell morphology and presence of tumor-infiltrating lymphocytes, both parameters of adverse prognosis." (PMID 34638249, 2021). "Finally, in vivo tumor xenograft experiments were performed with nude mice to elucidate the effects associated with HOXA10-mediated HDAC1 regulation of DNMT1/KLF4 on the tumorigenic ability of LAD." (PMID 33596966, 2021). "Additionally, a high rate of HDAC1 expression has been significantly associated with tumour dedifferentiation." (PMID 32397189, 2020).
tumor (continued). "First, we examined whether Hdac1‐deficient tumor cells retained the increased H3K79 methylation levels seen prior to the oncogenic transformation." (PMID 31304633, 2019). "In this study, we aimed to reveal the mechanisms underlying the tumor-promoting effects of 3MC in RECs, with a particular focus on HIF1α/HDAC1 and RhoA, and to determine whether simvastatin can prevent these effects." (PMID 30872677, 2019). "For example, the ability of HDAC1, 2 and 3 deacetylases to be either upregulated or downregulated in a patient-dependent manner indicates the decisive role of a tumor’s specific mutational signature to tightly control each HDAC enzyme’s expression and activity." (PMID 30875794, 2019). "Sun and colleagues demonstrated that miR-34a expression is negatively associated with HDAC1, and that miR-34a may act as a tumour suppressor gene regulating HDAC1 expression and inducing cell cycle arrest and apoptosis in HCC." (PMID 30533999, 2018). "Interestingly, we observed that mono-allelic expression of Hdac2 in Hdac1-deficient Eμ-myc B cells (Hdac1Δ/Δ; Hdac2Δ/+) resulted in delayed tumor development, whereas complete Hdac1 and Hdac2 deletion (Hdac1Δ/Δ; Hdac2Δ/Δ) prevented tumorigenesis altogether." (PMID 27886239, 2016). "Notably, elevated HDAC-1 expression was significantly associated with increased tumor proliferative capacity, enhanced HDAC-4 expression with the absence of distant metastases and elevated HDAC-6 expression with earlier histopathological stage." (PMID 26502922, 2015). "Besides the distinct presence of class I HDACs in urothelial cancer, high expression levels of HDAC-1 and -2 were associated with stage and grade of this tumours." (PMID 24624923, 2014). "For instance, low expression of HDAC1/HDAC2 in the epidermis might cause a predisposition towards neoplasia." (PMID 24240174, 2013). "Importantly, co-repressor associated deacetylase was significantly reduced for Sin3A, NuRD and Co-REST complexes in HDAC1-deficient tumours compared to wild-type tumours." (PMID 24240174, 2013). "Therefore, ligand mediated AHR activation might contribute to the tumor promoting effects associated with HDAC1." (PMID 37696456, 2023). "Increased Cyt maspin may be causative in ECA/GEJ Aca development and progression since the molecular mechanism underlying the tumor suppressive effect of maspin is, at least in part, through its direct inhibition of nuclear HDAC1 and HDAC1-dependent transcriptome." (PMID 31002675, 2019). "Similarly, loss of HDAC1 in human tumour cells led to reduced proliferation and elevated apoptosis." (PMID 24240174, 2013). "Among the PCNA-associated hubs, ATM, HDAC1, and MDM2 showed strong correlations with the infiltration of multiple immune cells, highlighting their roles in tumor–immune interactions." (PMID 40430573, 2025). "Using TIMER 2.0, we observed a positive correlation between HDAC1, 2, and 3 expression and tumor-infiltrating MDSCs in LIHC." (PMID 39891718, 2025). "Collectively, our findings demonstrate that the acetylation of GCDH at lysine 438 (K438), mediated by P300 and HDAC1, plays a vital role in the tumor-suppressive activities of HCC cells." (PMID 40896397, 2025). "For example, ICBP90, an E2F-1 target, recruits HDAC1 to promoter regions of various tumor suppressor genes, thus promoting tumor cell proliferation." (PMID 40701951, 2025). "In turn, hydroxamic acids containing a bicyclic pinane framework in the cap group inhibit HDAC1 of tumor cells, due to their high affinity for HDAC1, due to the formation of hydrogen bonds with the enzyme allosteric center." (PMID 40943548, 2025). "Our findings underscore the tumor-suppressive function of HDAC1 and HDAC2 in T cells during ALCL development." (PMID 40175628, 2025). "Tumor growth curves revealed that both EA and HDAC1 inhibitor retarded tumor progression compared to the vehi group." (PMID 40475010, 2025).
tumor (continued). "The data presented suggest that Ikaros exerts its tumor suppressor function in T-ALL by recruitment of HDAC1." (PMID 40555735, 2025). "We examined HDAC1 and HDAC7 expression in postoperative tumor specimens and assessed their association with overall prognosis." (PMID 41444923, 2025). "Among them, compound St.2 exhibited potent HDAC1 inhibition and strong antiproliferative activity across various tumor cell lines." (PMID 41440016, 2025). "RCOR2 hijacked LSD1- and HDAC1/2-dependent epigenetic programs to promote tumor plasticity and immune evasion, respectively." (PMID 40608411, 2025). "In our study, comprehensive analyses utilizing mRNA sequencing data from The Cancer Genome Atlas (TCGA) have demonstrated that HDAC1 expression is markedly elevated in 16 different tumor types including BRCA compared to normal tissues." (PMID 40475010, 2025). "This study aims to investigate the therapeutic effects of peritumoral EA combined with HDAC1 inhibitor on tumor growth, specifically focusing on the the potential of peritumoral EA as a novel therapeutic strategy to enhance immune responses for TNBC in mice." (PMID 40475010, 2025). "To explore the therapeutic potential of HDAC1 inhibitor in enhancing EA-mediated tumor suppression, we meticulously assessed tumor growth curve, bioluminescence imaging, tumor weight, and systemic pro-tumorigenic cytokine levels in the TNBC transplant model." (PMID 40475010, 2025). "This inhibitory effect largely depends on the interaction among HIF-1α, PRC2, and HDAC1, which induces chromatin remodeling, resulting in epigenetic suppression of these tumor-killing cytokines." (PMID 39133578, 2024). "Tumour cell line sensitivity to kinase inhibitors was associated with upregulation of HDAC5, HDAC1, and several SIRT genes." (PMID 38369747, 2024). "Our study demonstrates that Paromomycin acts as an HDAC1 inhibitor, reversing detrimental epigenetic modifications that fuel tumor growth and survival." (PMID 39723246, 2024). "The results demonstrated a robust enrichment of ZEB1 and HDAC1 on the promoters of CLDN7 and ANXA7, all of which are implicated in tumor suppression." (PMID 39193340, 2024). "The strong correlation between HDAC1 mRNA expression and tumor size further supports its central role in the preconstructed prognostic model." (PMID 39512688, 2024). "We confirmed HDAC1/2 expression in tumor organoids, with the embryonal tumors expressing higher levels of HDACs than the fetal tumors." (PMID 39567475, 2024). "High levels of HDAC1 in GBM significantly contribute to aggressive tumor behavior, enhancing cell proliferation, migration, and resistance to apoptosis." (PMID 39723246, 2024). "We also found that hbl107, hbl109, and hbl111 cells are positive for HDAC1 and that they form HDAC1-positive tumor clusters." (PMID 39001363, 2024). "REN maps on chromosome 17p, a region frequently deleted in SHH-MB subgroup, and acts as tumor suppressor which, by promoting degradation of HDAC1, inhibits GLI1 activity and represses SHH-MB growth." (PMID 38062245, 2024). "The overexpression of HDAC1 correlates with the inhibition of tumor suppressor genes and activation of oncogenic pathways, thereby promoting tumor growth and survival." (PMID 39723246, 2024). "The effect of these drugs on the number of cells, formation of tumor clusters and HDAC1-Sp5-p21 axis were examined." (PMID 39001363, 2024). "BRCA1 and HDAC1 exhibited significantly elevated expression in tumor samples, while RANGAP1 demonstrated significantly decreased expression in tumor samples." (PMID 38801243, 2024). "We next asked if genetic deletion of either HDAC1 or 2 or of both would show similar effects on tumor cell growth in vivo as those observed in vitro." (PMID 37598220, 2023).
tumor (continued). "At the same time, due to its important role in tumor genesis and development, this study provides a theoretical basis for the HDAC1 target therapy of LUAD." (PMID 36644230, 2023). "Class I HDACs and class III HDACs have tumor suppressor functions: conditional knockout mice for Hdac1 and Hdac2 develop lymphoid malignancies, as well as non-hematopoietic tumors." (PMID 35328416, 2022). "As shown by bioluminescence imaging and HE staining, HDAC1 silencing resulted in fewer nodules visualized on the liver surface and nodules formed in the liver of tumor-bearing nude mice 4 weeks later." (PMID 35395834, 2022). "It seems that LSD1 and HDAC1 function either as a tumor suppressor or enhancer, depending on the cellular context and tumor stage." (PMID 36566195, 2022). "Correlations of the EMD score with tumor mutation burden, tumor purity, aneuploidy score, tumorigenic pathways, TME characteristics, and FTO/HDAC1 ratio were measured." (PMID 35600848, 2022). "Both H6M and H6AQ were noted to have higher HDAC1 and tumor cell inhibitory abilities than the positive control SAHA." (PMID 35056740, 2022). "In our study, there was a positive correlation between HDAC1 expression levels and tumor purity, and CD8+ T cells', CD4+ T cells', neutrophils', and dendritic cells' infilitration levels." (PMID 35845599, 2022). "For example, the histone deacetylase gene HDAC1 was upregulated across all sample groups except for LB fHER2− tumours, and the histone deacetylase gene HDAC2 was only upregulated in CLs." (PMID 36220861, 2022). "As confirmed by histological analysis, oral administration of GA for 8 weeks decreases tumor size, damages tumor structure, and lowers expression of HDAC1 and PCNA in tumor mass." (PMID 36233012, 2022). "Another major difference is that loss of HDAC1 promotes tumorigenesis in mouse thymocytes, whereas in human CTCL loss of HDAC activity has anti-tumor effects." (PMID 36425063, 2022). "Meanwhile, TPX2 overexpression diminished the inhibitory effect of HDAC1 silencing on tumor volume and weight of nude mice." (PMID 35395834, 2022). "Maspin was evidenced to be an endogenous HDAC1 inhibitor in prostate epithelial cells to epigenetically regulate certain gene expressions, which contribute to or favor its tumor-suppressing activities." (PMID 36523976, 2022). "Statistical analysis showed that the high‐HDAC1 expression group had worse nodal status (P = 0.003) and advanced tumor node metastasis (TNM) stage (P = 0.01); the high‐HDAC2 expression group had more patients with liver invasion (P = 0.03)." (PMID 35075805, 2022). "LSD1 and histone deacetylase 1 (HDAC1) have been demonstrated to repress the expression of genes related to tumor immunity and inflammation." (PMID 35938161, 2022). "Exosome-mediated RNF157 mRNA from PCa cells results in M2 macrophage polarization via destabilizing HDAC1, consequently promoting PCa tumor progression." (PMID 36263220, 2022). "Previous studies have confirmed that the five autophagy-related genes (BIRC5, SQSTM1, HDAC1, RHEB, and ATIC) are associated with tumor proliferation, apoptosis, and resistance to anticancer agents in HCC patients." (PMID 35573678, 2022). "In all cases, the expression of either inactive HDAC1 or HDAC2 was sufficient to sensitize cells for tumor drug treatment." (PMID 35994477, 2022). "Based on the IHC results of HDAC1, ‐2 and ‐6 expression in tumour tissues, all 100 GBC samples were categorized into low‐expression and high‐expression groups." (PMID 35075805, 2022). "An analysis of the mean z-score in each data set revealed that DNMT3A, DNMT3B, and HDAC1/2/3 tended to have positively shifted z-scores indicating an increase in mean gene expression in the tumor populations." (PMID 36050516, 2022). "Previous studies have also demonstrated that HDAC1 modulates the senescence process of HCC cells, as well as that inhibiting HDAC1 expression induces apoptosis in tumor cells." (PMID 36275676, 2022).
tumor (continued). "qPCR experiments verified that the expressions of MAP7, CDK1, PPP3R1, PRKC1, CCND1 and HDAC1 genes were indeed altered in AT/RT tumor tissue." (PMID 35524230, 2022). "Our results also confirmed that HDAC1 was correlated with tumor occurrence, development, and clinical prognosis." (PMID 35686089, 2022). "Studies have shown that genome-wide histone acetylation levels are generally reduced in tumor cells, among which HDAC1, HDAC5 and HDAC7 are regarded as tumor markers." (PMID 35545840, 2022). "For example, HDAC1 expression is positively correlated with proliferative activity, degree of tumor differentiation, and TNM staging." (PMID 35327319, 2022). "We demonstrated that the protein levels of HDAC1, 2, and 3 exhibited a graded increase from normal and benign UF tumor cells to malignant uLMS cells (p < 0.05)." (PMID 36497061, 2022). "Thereby, HDAC1 stimulates oxygenation of the tumor microenvironment by upregulating HIF-1α expression through HDAC1/MTA1." (PMID 35327319, 2022). "The authors presented a dosage-dependent model of HDAC1 and HDAC2 in tumor suppression, with the HDAC1 being the key histone deacetylase in thymocytes." (PMID 35887172, 2022). "In particular, we confirmed that KIT‐targeting drugs, such as pazopanib, are potentially adequate to target POU2F3‐driven SCLCs, whereas YAP1‐driven tumours are more resistant to vorinostat (targeting HDAC1)." (PMID 36149789, 2022). "Resistance of tumor cells to T cell–mediated killing by the NANOG/HDAC1 axis is essential for inducing the immune-refractory feature in the TME." (PMID 35104240, 2022). "The results showed that HDAC1, 2, 3, 6, 7, 8, and 9 were significantly upregulated in tumor tissues compared to that in normal tissues." (PMID 35989326, 2022). "Taken together, LSH‐A54 is a slow‐binding, selective HDAC1/2 inhibitor with encouraging effects on tumor cell dynamics and thus invasive properties for tissue colonization." (PMID 35073610, 2022). "Further, HDAC1 was proven to be a tumor-facilitator in NB, and SNORA50C contributed to NB cell growth and migration through the HDAC1-mediated pathway." (PMID 35821006, 2022). "HDAC1 inhibition sensitizes NANOGhi-refractory tumor cells to anti–PD-1 therapy by reinvigorating the antitumor immunity cycle." (PMID 35104240, 2022). "The in vivo experimental data illustrated that HDAC1 silencing led to reductions in tumor volume, tumor size, and weight in nude mice." (PMID 35395834, 2022). "HDAC-1 was overexpressed in tumor tissue compared to adjacent normal liver tissue, being correlated with poor tumor grade differentiation." (PMID 34441281, 2021). "We demonstrate marked suppression in tumor growth upon targeting of HDAC1 and identify compensatory pathways that provide insights into combination therapies for GBM." (PMID 34494550, 2021). "Patients with a higher percentage of tumor cells positively immune-stained for HDAC1 and HDAC2 expressions were more likely to experience shorter disease-free survival, as well as higher T and N stages, and triple-negative pathology." (PMID 34580286, 2021). "Genetic analysis of the role of individual HDAC class I genes by CRISPR/Cas9 knockouts showed that both HDAC1 and 2 expression are essential for proliferation, invasiveness and local tumor growth of EwS cells." (PMID 34654445, 2021). "In our cohort, increased cytoplasmic HDAC-1 expression was indeed correlated with increased tumor size, whilst the correlation of HDAC-2 immunoreactivity with tumor size was not straightforward." (PMID 34638249, 2021). "HDAC1 knockdown in GSCs markedly attenuates their ability to form tumors and increases survival of tumor-bearing mice." (PMID 34494550, 2021). "Mechanistically, HDAC1 inactivation leads to the deregulated expression of lineage-defining TFs such as C/EBPα, enhancing the undifferentiated state of tumour cells." (PMID 34298745, 2021). "As was found in this study, with the progression of tumours, the difference in HDAC1 gradually became significant." (PMID 34966737, 2021).